FUS (FUS RNA binding protein)
Diseases named in the same sentence as FUS in open-access papers (continued):
Sharing a sentence is not in itself a finding about the gene and the disease.
amyotrophic lateral sclerosis (continued). "Mutations in FUS lead to the mislocalization of FUS from the nucleus to the cytosol and formation of pathogenic aggregates in neurodegenerative diseases including amyotrophic lateral sclerosis (ALS) and frontotemporal lobar dementia (FTLD), yet with unknown molecular mechanisms." (PMID 37123224, 2023). "Another known C-terminal motif our analysis identified is a FUS mutation of a phosphorylation site that is causative for juvenile amyotrophic lateral sclerosis (JALS), a subtype of ALS." (PMID 36830724, 2023). "Another example of mutations in three important spliceosomal maintenance proteins (TDP-43, FUS/TLS, and SMN) cause profound loss of the spliceosomal integrity and lead to amyotrophic lateral sclerosis (ALS) and spinal muscular atrophy (SMA)." (PMID 38047291, 2023). "In amyotrophic lateral sclerosis (ALS), disease-associated mutations are thought to alter the capacity of TDP-43 and FUS to participate in complexes mediated by phase separation, disrupting their normal function." (PMID 36980167, 2023). "Mutations in FUS and TBK1 often cause aggressive early-onset amyotrophic lateral sclerosis (ALS) or a late-onset ALS and/or frontotemporal dementia (FTD) phenotype, respectively." (PMID 34518945, 2022). "FUS and TDP-43 are essential proteins, but their anomalous aggregation has been implicated in amyotrophic lateral sclerosis (ALS) and frontotemporal dementia (FTD)." (PMID 35658951, 2022). "Mutations in the RBPs, TAR DNA (TARDBP), FUS RNA-binding protein (FUS), Ataxin 2 (ATXN2) as well as EWS RNA-binding proteins (EWSR1) and many more have been shown to greatly influence disease risks, e.g., amyotrophic lateral sclerosis (ALS) and frontotemporal dementia (FDT)." (PMID 35202165, 2022). "The genetic mutation of FUS is a DNA/RNA binding protein that can cause frontotemporal degeneration (FTLD) and amyotrophic lateral sclerosis (ALS)." (PMID 34138931, 2021). "Mutations in Fused in Sarcoma (FUS) are present in familial and sporadic cases of amyotrophic lateral sclerosis (ALS) and frontotemporal dementia (FTD)." (PMID 34475430, 2021). "Amyotrophic lateral sclerosis (ALS) and frontotemporal dementia (FTD) share a common mechanism for mitochondrial toxicity and neurodegeneration caused by protein misfolding and aggregation of mutant superoxide dismutase 1 (SOD1), TAR DNA-binding protein 43 (TDP-43), and RNA-binding protein FUS." (PMID 33922020, 2021). "Xrp1 has been shown to play a role in a Drosophila model of Amyotrophic lateral sclerosis (ALS), a debilitating and lethal neurodegenerative disorder that can be caused by aggregogenic mutations in genes encoding RNA binding proteins, including TDP-43 and FUS, a member of the FET family of proteins." (PMID 34914692, 2021). "Since 2009, more than 60 mutations in fused in sarcoma (FUS), also known as translocated in liposarcoma (TLS), have been identified to be associated with the two overlapping adult-onset neurodegenerative diseases: amyotrophic lateral sclerosis (ALS) and frontotemporal dementia (FTD)." (PMID 33407930, 2021). "Several amyotrophic lateral sclerosis (ALS)-related proteins such as FUS, TDP-43, and hnRNPA1 demonstrate liquid–liquid phase separation, and their disease-related mutations correlate with a transition of their liquid droplet form into aggregates." (PMID 34774801, 2021). "Mutations in DNA/RNA‐binding factor (fused‐in‐sarcoma) FUS and superoxide dismutase‐1 (SOD‐1) cause amyotrophic lateral sclerosis (ALS)." (PMID 31867846, 2020). "The amyotrophic lateral sclerosis (ALS) and frontotemporal dementia (FTD)–linked RNA-binding protein called FUS (fused in sarcoma) has been implicated in several aspects of RNA regulation, including mRNA translation." (PMID 33082139, 2020). "FUS and TDP-43 are frequently studied proteins because their phase separation in vivo has been linked to amyotrophic lateral sclerosis (ALS)." (PMID 31694155, 2019).
amyotrophic lateral sclerosis (continued). "It has been shown that mutation in FUS and TARDBP are related to amyotrophic lateral sclerosis(ALS), a motor neuron disease by leading to neuronal cell death." (PMID 31017923, 2019). "Mutations in the fused in Sarcoma (FUS) gene induce cytoplasmic FUS aggregations, contributing to the neurodegenerative disease amyotrophic lateral sclerosis (ALS) in certain cases." (PMID 31244613, 2019). "FUS and TDP43 are linked to Amyotrophic lateral sclerosis (ALS), a progressive motor neuron dysfunction disease." (PMID 32010626, 2019). "Cytoplasmic aggregation of fused in sarcoma (FUS) is detected in brain regions affected by amyotrophic lateral sclerosis (ALS) and frontotemporal dementia (FTD), which compose the disease spectrum, FUS proteinopathy." (PMID 28928015, 2017). "Deposition of TDP-43 has been also been detected in some patients with amyotrophic lateral sclerosis (ALS), in consonance with the fact that these two diseases share some clinical and genetic features such as mutations the in TARDBP, FUS and C9orf72 genes." (PMID 27138926, 2016). "FET-proteins are also involved in neurological diseases with FUS and TAF15 mutations identified in familial amyotrophic lateral sclerosis (ALS), frontotemporal lobar degeneration (FTLD) and essential tremor disorders." (PMID 26573619, 2015). "Another recent discovery suggests that mutations in FUS (fused in sarcoma), a DNA repair protein that associates with the HDAC1-SIRT1 repair complex, result in the accumulation of DNA strand breaks, neurodegeneration and neurological defects in amyotrophic lateral sclerosis (ALS)." (PMID 25590633, 2015). "TDP-43 and FUS are RNA-binding proteins that form cytoplasmic inclusions in someforms of amyotrophic lateral sclerosis (ALS) and frontotemporal lobardegeneration (FTLD)." (PMID 21541367, 2011). "Amyotrophic lateral sclerosis (ALS) is characterised by the aggregation of TDP-43 and mutant FUS in the cytoplasm of affected motor neurons." (PMID 42086533, 2026). "In neurological diseases such as amyotrophic lateral sclerosis, the interaction between DDX17 and mutant FUS proteins is involved in neuronal protection." (PMID 41322492, 2025). "While C9orf72 repeat expansions are connected to changed ER–mitochondria contacts in amyotrophic lateral sclerosis (ALS), pathogenic mutations in TDP-43 and FUS disrupt calcium signaling and mitochondrial bioenergetics by interfering with MAM-resident tethering proteins." (PMID 41002898, 2025). "In amyotrophic lateral sclerosis (ALS), the FUS protein typically aids DNA repair through phase separation." (PMID 40429758, 2025). "Indeed, the yeast AAA + protein disaggregase, Hsp104, has been engineered to rescue the proteotoxicity of TDP43, FUS, and α-synuclein for amyotrophic lateral sclerosis (ALS) and Parkinson’s disease." (PMID 39824813, 2025). "Amyloid fibril structures derived from self-assembly IDPs have been determined, such as the RNA-binding protein FUS, the RNA-processing protein hnRNPA2, and TDP-43, which is associated with amyotrophic lateral sclerosis (ALS) and frontotemporal lobar degeneration." (PMID 41446360, 2025). "In amyotrophic lateral sclerosis (ALS), glycine and proline residues maintain FUS protein liquidity, while serine and glutamine residues promote its liquid–solid transition." (PMID 40723369, 2025). "Examples of these are Ataxia teleangiectatica—caused by autosomal recessive mutations in the ATAXIA TELEANGIECTASIA MUTATED (ATM) gene—or Amyotrophic lateral sclerosis (ALS)—caused, among others, by autosomal dominant mutations within the FUSED IN SARCOMA (FUS) gene." (PMID 38542501, 2024). "The search for FUS was motivated by the discovery that rare mutations in FUS can cause the motor disorder amyotrophic lateral sclerosis (ALS) in the absence of FTLD16,17." (PMID 38057661, 2024).
amyotrophic lateral sclerosis (continued). "FUS, a prion-like protein containing intrinsically disordered domains, combines with several splicing factors to form FUS interactors that participate in abnormal RNA metabolism in the neurodegenerative disease amyotrophic lateral sclerosis (ALS)." (PMID 39199340, 2024). "Post-mortem examination of spinal cord tissue from amyotrophic lateral sclerosis (ALS) patients consistently reveals the presence of TDP-43-, FUS- or SOD1- and ubiquitin-positive inclusions comprised of insoluble proteinaceous material." (PMID 38879591, 2024). "The regulation of VAPB-PTPIP51 in amyotrophic lateral sclerosis and frontotemporal dementia (ALS/FTD) by FUS metabolism defects through GSK3β mediated regulation of complex formation and supports disease development." (PMID 38434478, 2024). "FET proteins are relevant in several different cancers and point mutations in either FUS or TAF15, some of which affect their nuclear–cytoplasmic shuttling, can cause neurodegenerative diseases such as amyotrophic lateral sclerosis (ALS) and frontotemporal lobar dementia (FTD)." (PMID 38568213, 2024). "Moreover, it was revealed that PAD4 can competitively inhibit the methylation of some RGG motif proteins including the FET proteins (FUS, EWS and TAF15) and hnRNPA1, and each has been linked to amyotrophic lateral sclerosis (ALS)." (PMID 37778382, 2023). "EWS and TAF15 (as well as FUS) can localize to cytoplasmic stress granules and paraspeckles and pathologically accumulate as cytosolic inclusions in patients with amyotrophic lateral sclerosis (ALS) and frontotemporal lobar degeneration (FTLD)." (PMID 36833257, 2023). "The role of the fused in sarcoma (FUS) RNA-binding protein, responsible for the regulation of RNA, has been reported in amyotrophic lateral sclerosis (ALS) and frontotemporal dementia, but there are only a few reports on its role in cancer." (PMID 36517760, 2022). "In addition, PARP1 promotes the formation of TDP-43- and FUS-rich granules in the cytoplasm, two RNA-binding proteins which form neuronal cytoplasmic inclusions observed in certain neurodegenerative diseases such as amyotrophic lateral sclerosis and frontotemporal lobar degeneration." (PMID 36497190, 2022). "SMN interacts with the fused in sarcoma (FUS) protein, a genetic factor in amyotrophic lateral sclerosis, which links the two motor neuron diseases." (PMID 36114190, 2022). "In amyotrophic lateral sclerosis (ALS) and frontotemporal dementia (FTD), FUS mislocalizes to the cytoplasm where it forms insoluble aggregates." (PMID 34021139, 2021). "Importantly, the mislocalization of RBPs, such as TDP-43, FUS and hnRNP A1, is a histopathological feature of several neurodegenerative diseases, including amyotrophic lateral sclerosis (ALS) and frontotemporal dementia (FTD)." (PMID 34630013, 2021). "Recent studies showed that such aberrant phase transitions are also involved in neurodegenerative diseases, affecting neuronal proteins such as Fused in Sarcoma (FUS) in Amyotrophic Lateral Sclerosis (ALS), Tau in Alzheimer's disease (AD) and huntingtin exon 1 in Huntington's disease (HD)." (PMID 33138914, 2020). "At the same time, potentiated variants of Hsp104 have been engineered to disaggregate misfolded proteins of higher eukaryotes, connected with PD (α-synuclein) and amyotrophic lateral sclerosis (ALS) (TDP-43 and FUS)." (PMID 31540362, 2019). "Furthermore, FUS aggregation has been observed in amyotrophic lateral sclerosis (ALS), frontotemporal dementia (FTD), and the polyglutamine diseases, which include Huntington disease, spinocerebellar ataxia, and dentatorubropallidoluysian atrophy." (PMID 31240261, 2019). "Mutations of Fused in sarcoma (FUS), a ribonucleoprotein involved in RNA metabolism, have been found associated with both familial and sporadic cases of amyotrophic lateral sclerosis (ALS)." (PMID 30872738, 2019).
amyotrophic lateral sclerosis (continued). "Several genes have been linked to the onset of amyotrophic lateral sclerosis (ALS, OMIM # 105400), including SOD1, C9ORF72, TARDBP, and FUS, though roughly 80% of cases are of unknown etiology." (PMID 29776328, 2018). "Aggregation of many RBPs, such as TIA-1, FUS, TDP43, hnRNPA1 and hnRNPA2 in Amyotrophic lateral sclerosis/frontotemporal dementia (ALS/FTD) proteinopathies are mediated by prion-related domain (PRD)." (PMID 30367664, 2018). "Dysregulation of RNA metabolism represents an important pathogenetic mechanism in both amyotrophic lateral sclerosis (ALS) and frontotemporal dementia (FTD) due to the involvement of the DNA/RNA-binding proteins TDP-43 and FUS and, more recently, of C9ORF72." (PMID 27151080, 2016). "The genes for four proteins involved in this process (TDP43, FUS, VCP, and CHMP2B) have mutations in various familial cases of the neurodegenerative diseases fronto-temporal dementia (FTD) or amyotrophic lateral sclerosis (ALS)." (PMID 27242399, 2016). "FUS and EWS are identified in translocation generated cancer fusion proteins and involved in the human neurological diseases amyotrophic lateral sclerosis and fronto-temporal lobar degeneration." (PMID 26573619, 2015). "TDP-43 and FUS mutations are found in amyotrophic lateral sclerosis (ALS) and frontotemporal lobar degeneration (FTLD), and mutations in hnRNPA1 and hnRPNPA2/B1 have also been found in ALS." (PMID 25719440, 2015). "The major aggregating proteins in amyotrophic lateral sclerosis (ALS) are superoxide dismutase 1 (SOD1), TDP-43 (TARDBP) and FUS." (PMID 25358814, 2014). "Interestingly, several upregulated DE genes were related to neurodegenerative diseases, such as genes related to Alzheimer’s disease: PSEN2, TREM2, and GAB2; Parkinson’s disease: ATP13A2 and DCTN1; and amyotrophic lateral sclerosis: TAF15 and FUS." (PMID 40877796, 2025). "Aberrant LLPS has been implicated in the formation of amyloid-like aggregates in diseases such as amyotrophic lateral sclerosis (ALS) and frontotemporal dementia (FTD), where phase-separated intermediates composed of IDPs, such as FUS and TDP-43, transition to pathological solid states." (PMID 40407495, 2025). "The pathogenic proteins most commonly implicated in the accumulation of “misfolded” brain aggregates include, among the others, tau and β-amyloid in AD, α-synuclein in PD, huntingtin in HD and FUS, ZNF and TDP-43 in amyotrophic lateral sclerosis (ALS) and Fronto-Temporal Dementia (FTDs)." (PMID 38993838, 2024). "A functional link between FUS and TDP-43 may explain their common implication in amyotrophic lateral sclerosis." (PMID 38311174, 2024). "Amyloid protein aggregates, such as FUS and TDP-43 aggregations in Amyotrophic Lateral Sclerosis (ALS), Tau and Aβ aggregations in Alzheimer’s disease (AD), and α-synuclein fibrils in Parkinson’s disease (PD), are pathognomonic features of several neurodegenerative diseases." (PMID 36835140, 2023). "Depletion or mutations in genes encoding RBPs like TDP-43 (TAR DNA-binding protein 43), FUS (fused in sarcoma), and FMRP (fragile X mental retardation protein) leads to human neurological disorders such as spinal muscular atrophy, amyotrophic lateral sclerosis, and fragile X syndrome." (PMID 36758804, 2023). "Moreover, mislocalization of RBPs outside the nucleus such as FUS, TAF15, hnRNP A1, hnRNP A2, and TDP‐43 leads to amyotrophic lateral sclerosis and frontotemporal dementia." (PMID 36875159, 2023). "FET (FUS-Fused in Sarcoma; EWSR1-Ewings Sarcoma breakpoint region 1; TATA box binding protein Associated Factor 15) proteins have been implicated in neurodegenerative disorders such as Amyotrophic Lateral Sclerosis (ALS) and Fronto-Temporal Lobar Degeneration (FTLD)." (PMID 35440550, 2022). "However, there are number of genes, including the TDP-43 and FUS proteins, which induce FTD but are also involved in amyotrophic lateral sclerosis." (PMID 35203354, 2022).
amyotrophic lateral sclerosis (continued). "In addition, the RNA binding protein FUS, which is mutated in Amyotrophic lateral sclerosis (ALS), associates with the SMN complex via direct interaction with SMN, suggesting a common biochemical pathway between ALS and SMN." (PMID 34458251, 2021). "These include TDP43, FUS, hnRNPA1, PSF/SFPQ and p54/NONO, all of which have been linked to neurodegeneration associated with amyotrophic lateral sclerosis and frontotemporal dementia." (PMID 29426953, 2018). "The RNA-binding proteins TDP-43 (TAR DNA-binding protein of 43 kDa) and FUS (Fused in sarcoma) have become infamous over the past years as being the main culprits in two fatal neurodegenerative diseases, ALS (amyotrophic lateral sclerosis) and FTD (frontotemporal dementia)." (PMID 29728564, 2018). "Importantly, many RBPs have been shown to have strong genetic links to neurodegenerative disease; for example, mutations in TDP-43, FUS, hnRNPA1, and ATXN2 have all been shown to cause amyotrophic lateral sclerosis (ALS), frontotemporal lobar degeneration (FTLD) and/or spinocerebellar ataxia." (PMID 30068389, 2018). "It is also reminiscent of the aberrant aggregation-dependent cytosolic migration seen for nuclear RNA-binding proteins with LCDs such as TDP-43, fused in sarcoma (FUS), or hnRNP-A1 which aberrantly accumulate in the cytosol in diseases such as amyotrophic lateral sclerosis." (PMID 29023495, 2017). "TDP-43 positive, but FUS negative, inclusions in the spinal cord are consistent with classical features of late-onset amyotrophic lateral sclerosis." (PMID 29286334, 2017). "Finally, familial amyotrophic lateral sclerosis (ALS) may result from mutations in the genes for TDP43, FUS, C9ORF72 and, classically, SOD1." (PMID 26035384, 2015). "Amyotrophic lateral sclerosis (ALS) studies using RNA-seq have identified dysregulated RNA-binding proteins such as TDP-43 and FUS, which are crucial for RNA stability and splicing, offering insights into disease pathophysiology." (PMID 40004464, 2025). "In the context of amyotrophic lateral sclerosis (ALS), lines expressing mutant forms of SOD1, TDP-43, or FUS recapitulate motor neuron degeneration and neuromuscular junction damage, allowing real-time imaging of disease progression and therapeutic testing." (PMID 41302176, 2025). "Two proteins, namely fused in sarcoma (FUS) and TAR DNA binding protein-43 (TDP-43), are known to induce hyperactivation of GSK-3β and lead to amyotrophic lateral sclerosis (ALS)." (PMID 40148800, 2025). "None of the MFN2-amyotrophic lateral sclerosis patients tested positive for the pathogenic C9orf72 gene expansion, nor did they exhibit mutations in the SOD1 gene or the known mutational hotspots of the TARDBP (exon 6) and FUS (exons 13-14-15) genes." (PMID 39315308, 2024). "FUS and TDP-43 are closely related in structure, function and implication in diseases such as Amyotrophic Lateral Sclerosis (ALS)." (PMID 38807229, 2024). "Here, we present the PTMs and PTVs of four major amyotrophic lateral sclerosis (ALS) proteins, SOD1, TDP-43, FUS, and TBK1." (PMID 39201350, 2024). "Decreased affinity of Kapβ2 and FUS leads to aberrant cytoplasmic localization of FUS11, which is observed in amyotrophic lateral sclerosis (ALS) pathology." (PMID 34489423, 2021). "Further: The inclusions of FTLD-FUS include other FET proteins (transportin, TAF15 and EWS) and these are not seen in the MND-FUS cases FET proteins TAF15 and EWS are selective markers that distinguish FTLD with FUS pathology from amyotrophic lateral sclerosis with FUS mutations." (PMID 35002606, 2021). "In addition to tauopathies, the presence of GVBs has been studied in the brains of patients with other neurodegenerative proteinopathies, including human prion diseases, α-synucleinopathies and TDP-43- and FUS-related FTLD and amyotrophic lateral sclerosis (ALS)." (PMID 32883341, 2020).